IL10 (interleukin 10)
Diseases named in the same sentence as IL10 in open-access papers (continued):
Sharing a sentence is not in itself a finding about the gene and the disease.
psoriasis (continued). "Thus, it is possible that suppression of IL-23-mediated psoriasis-like inflammation by Bregs was mainly IL-10-dependent." (PMID 33483537, 2021). "Similarly, in the IMQ-induced psoriasis mouse model, a subset of IL-10-producing B cells was identified, and adoptive transfer of these IL-10-producing B cells reduced disease severity." (PMID 34616394, 2021). "Strategies to upregulate local or systemic production of IL-10 in patients with psoriasis could help increasing the effectiveness of current therapies." (PMID 34616394, 2021). "In the spleen, the frequencies of IL-10-producing B cells was significantly increased in Cd19Cre+/−PtenloxP/loxP mice compared to those in Cd19Cre+/− mice during all courses of IL-23-mediated psoriasis-like inflammation (P < 0.05 and P < 0.001)." (PMID 33483537, 2021). "Our results revealed significantly increased levels of the tested proinflammatory cytokines and a decrease in IL-10 concentration in unstimulated and stimulated saliva of psoriasis patients with normal salivation (except for TNF-α in NWS and INF-γ in SWS) and hyposalivation compared to the controls." (PMID 32164227, 2020). "Thus, we next examined the IL-10 and IL-23 expression by DCs, a key cell type in the pathogenesis of psoriasis." (PMID 32456211, 2020). "TLR2 signaling promotes IL-10 production from DCs and Tregs and proliferation of Tregs, resulting in a decreased production of inflammatory cytokines and a marked attenuation of imiquimod-induced psoriasis skin inflammation." (PMID 33202847, 2020). "Results from a pooled analysis conducted by us also indicated that levels of interferon-γ, IL-17, IL-23, and tumor necrosis factor-α were significantly increased, whereas those of IL-4 and IL-10 were significantly decreased in the sera of patients with blood-heat syndrome of psoriasis." (PMID 32228720, 2020). "Moreover, administration of recombinant IL‐10 significantly reduced the severity of psoriasis in humans." (PMID 30523673, 2019). "Given that IL‐10 played a protective role in inflammation development, adoptive transfer of B10 cells effectively suppressed imiquimod‐induced skin inflammation in a mouse model of psoriasis." (PMID 30523673, 2019). "Second, owing to low sample size of studies, the association of the IL‐1RN VNTR polymorphism and IL‐10 SNPs with psoriasis subtypes was not taken into account in our meta‐analysis." (PMID 30523673, 2019). "In addition, levels of IL‐10‐producing regulatory B cells (B10 cells) were decreased in patients with psoriasis." (PMID 30523673, 2019). "All this data supports the role of IL-10 in the pathogenesis of psoriasis and supports the idea that targeting IL-10 might be useful in psoriasis." (PMID 30744173, 2019). "It was observed that, after anti-CD3 and anti-CD28 stimulation, IL-10 levels were significantly lower in psoriasis patients treated with methotrexate and in patients on anti-TNF treatment than in healthy control subjects (p = 0.029 and p = 0.030, respectively)." (PMID 31101850, 2019). "Both IL‐1Ra and IL‐10 are important anti‐inflammatory cytokines in psoriasis pathogenesis." (PMID 30523673, 2019). "It was noted that the two studies evaluating IL‐10 haplotype and psoriasis risk did not reported a significant association." (PMID 30523673, 2019). "Interestingly, adaptive T-cell-derived cytokines IL17A, IL17F, IL17C, IL26, IFNG, IL4, and IL10 show comparable levels in skin biopsies from paradoxical and classical psoriasis." (PMID 29295985, 2018). "In psoriasis, T-cells (both CD4+ and CD8+) are known to cause low production of Th2 cytokines (IFNγ, TNFα, and IL-2) and high production of Th1 cytokines (IL-4, IL-6 and IL-10), leading to polarization of the type 1 pathway." (PMID 26849645, 2016).
psoriasis (continued). "It has been shown that serum levels of IFN-γ are much higher in patients with psoriasis than in controls and were correlated with the PASI score (psoriasis activity and severity index), whereas levels of Th2 cytokines (IL-4 and IL-10) were reported to be lower." (PMID 27274756, 2016). "Such decrease of IL10 secretion was also observed in patients with psoriasis receiving anti-IL12p40 therapies, but the exact mechanism was still unknown." (PMID 25761185, 2015). "In our study lesional IL-10 mRNA was higher in acne than in psoriasis." (PMID 25153527, 2014). "An in vitro study in peripheral blood mononuclear cells (231 cases and 345 controls) revealed an association between the CC genotype in rs16944 in the IL1β gene with increased production of IL1RA in response to lipopolysaccharide and IL10 and late-onset psoriasis (over 40 years)." (PMID 24069534, 2013). "Also, mice with psoriasis had significant increases in specific pro-inflammatory cytokines (IL-1β, IL-6 and IL-12) and decreases in the anti-inflammatory cytokine (IL-10) after PSD, which were normalized after 48 h of sleep rebound." (PMID 23226485, 2012). "Similarly, the pathogenesis of psoriasis involves key Th1 and Th17 inducing cytokines like TNFα, IL-1β, IL-2, IL-6, IL-10, IL-12p70, IL-23, CCL2, 3, 4, 5, 20, CXCL1, 8, 9 and 10, many of which are induced by cocktail treated DCs." (PMID 20663192, 2010). "Psoriasis is associated with over-expression of T-helper cell type 1 (Th1) cytokines, IFN-γ and TNF-α in the involved skin and relative underexpression of T-helper cell type 2 (Th2) cytokines, interleukin IL-4 and IL-10." (PMID 21152006, 2010). "IL10 is expressed in PBMCs of psoriasis, RA and IBD patients." (PMID 20444268, 2010). "One pilot and two Phase II trials with sc IL-10 administration over 3-7 weeks in patients with moderate to severe psoriasis have supported this hypothesis." (PMID 20101303, 2009). "Additionally, further exploration of the compensatory mechanisms of IL-10 in psoriasis could provide deeper insights into the interplay between systemic and local immune regulation in the disease." (PMID 40076417, 2025). "While the presence of IL-10 at the nail unit level is consistent with the established knowledge of the nail apparatus representing a site of relative immune privilege, finding a reason for the relative abundance of this cytokine in psoriasis-affected nails poses some challenges." (PMID 39598023, 2024). "In addition, a connection between anti-TNF treatment and IL-10 production has been proposed in multiple IMIDs: patients with juvenile idiopathic arthritis, psoriasis, RA, or Crohn’s disease were shown to have higher serum or cellular levels of IL-10 after treatment with anti-TNF." (PMID 39290825, 2024). "Moreover, Tregs from PsA patients produce less IL-10, as compared to psoriasis patients." (PMID 36450783, 2022). "Moreover, an obviously improvement in M1-related inflammation medicators (TNF-α, IL-6, NO and iNOs) and suppression in M2-related anti-inflammation cytokines (IL-10 and Arg-1) emerged in psoriasis lesions in the skins of IMQ-treated mouse, which was consistent with previous reports." (PMID 33858431, 2021). "Moreover, in a mouse model of imiquimod-induced psoriasis, a more severe skin inflammation observed in the CD19−/− mice in comparison to the wild type mice was indicative of the IL-10(+) CD1d(high)CD5(+) Bregs’ role in suppressing the psoriasis-like inflammation." (PMID 33669402, 2021). "Moreover, our findings have suggested TLR2 blocking agents, which may be developed soon, can exacerbate psoriasis by decreasing Tregs and IL-10 production." (PMID 33202847, 2020). "According to a cross-sectional study, psoriasis patients had increased proinflammatory macrophage type 1 (IL-1, IL-6, TNF-α), Th1 (IL-2, IL-12, IFN-γ), Th17 (IL-6, IL-17) but also anti-inflammatory Th2/T regulatory (Treg) (IL-4, IL-10) profiles which may be correlated to the severity of psoriasis." (PMID 31649677, 2019).
psoriasis (continued). "In light of investigations in psoriasis and atopic dermatitis, the role of dendritic cells in HS needs to be clarified, as dendritic cell influx has been reported in histological studies, and they may contribute to the high IL-10 and IL-15 levels reported." (PMID 30828428, 2018). "Thus, psoriasis remains the only example of disease where IL-10 therapy showed efficacy to control undesired immune reactions, most likely because IL-10 was injected at the site of inflammation, and could exert its immunosuppressive function locally." (PMID 29887861, 2018). "Furthermore, local administration of IL-10 reverses the pathological signatures of psoriasis." (PMID 29538330, 2018). "Moreover, the cytokines IL6 and IL10 seem to be important in the development of psoriasis." (PMID 24069534, 2013). "However, a sleep deprivation-dependent decrease in the anti-inflammatory cytokine (IL-10) was observed in both SHAM+PSD and PSO+PSD, suggesting sleep deprivation may be an important risk condition for psoriasis." (PMID 23226485, 2012). "We found that IL-10 is significantly associated with psoriasis GWAS whereas IL-22 is not." (PMID 21152006, 2010). "Previous studies have similarly reported elevated IL-10 levels in PLWH, with IFN-γ levels also being significantly higher in PLWH with psoriasis compared to healthy controls." (PMID 40572779, 2025). "Deucravacitinib inhibits the propagation of the type I interferon signals as well as other cytokines, including IL-10, IL-12, and IL-23, and is already FDA approved for the treatment of psoriasis." (PMID 40314052, 2025). "In psoriasis, Th1‐type cytokines such as IFN‐γ and IL‐2 are significantly increased, while the levels of Th2‐type cytokines like IL‐10 are relatively low, further promoting the immune response related to psoriasis." (PMID 40599237, 2025). "Since IL-10 inhibits production of pro-inflammatory cytokines such as IL-1, IL-6, and TNF-α, it can be useful for reducing inflammatory skin conditions, like psoriasis." (PMID 41465292, 2025). "In turn, hBD-2 in patients with psoriasis or RA increases the production of TNF-α, IFN-γ, IL-10, IL-1β, IL-6, and IL-22." (PMID 40062148, 2025). "In this study, TAN significantly inhibited the levels of iNOS, TNFα, IL-6, IL-10, IL-20, MIF, and MCP-1 in psoriasis mice, which had a wide range of inflammatory inhibitory effects." (PMID 38832986, 2024). "WT mice recovered well during the intervals between IMQ treatments, which was not suitable as an experimental model of chronic inflammatory reactions of psoriasis; however, psoriatic skin inflammation was maintained in IMQ-treated IL-10−/− mice." (PMID 37717073, 2023). "Through intragastric administration, CUR can alleviate psoriasis‐like lesions of mice by decreasing PASI scores, reducing the level of IL‐6, IL‐17A, IL‐22, IL‐23, TNF‐α, and TGF‐β1, promoting the expression of IL‐10." (PMID 37647442, 2023). "In the present study, we found that CB2R KO contributed to the pathogenesis of psoriasis by promoting CD4+ T cell proliferation; upregulating Th17 cytokines, such as IL-17A, IL-23A, and IL-17C; and downregulating IL-10." (PMID 35173615, 2022). "To confirm the mechanism by which CaMK4 inhibits IL-10 production through the Erk1/2 and p38 pathways found in mouse macrophages, we sorted peripheral CD14+ monocytes from patients with psoriasis." (PMID 35869084, 2022). "Upregulated inflammatory cytokines in the skin and peripheral blood of psoriasis patients, such as interferons, TNF-a, IL-1, IL-6 and IL-10, had an effect on erythropoiesis, leading to the enhanced RDW." (PMID 35213665, 2022). "In the present study, we showed that IL-10 neutralization enhanced skin inflammation, thickness and scaling in the IMQ-induced psoriasis mouse model beyond day 5, via upregulation of the IL-17/IL-19 axis." (PMID 34616394, 2021). "A total of 389 significant genes were common to both hepatitis C and psoriasis, which mainly involved IL6, TNF, IL10, ALB, STAT3 and CXCL8." (PMID 34215260, 2021).
psoriasis (continued). "The concentration of IL-10 (↓25.68%, p = 0.002; ↓47.30%, p ≤ 0.0001, respectively) in the NWS of psoriasis patients with normal and decreased saliva secretion was considerably lower than in the control group." (PMID 32164227, 2020). "Increased levels of TNF-α, IL-2, and INF-γ, as well as decreased content of IL-10 in NWS and SWS of psoriasis patients compared to the controls indicated an imbalance between Th1 and Th2 cells in the salivary glands." (PMID 32164227, 2020). "In the presented study, we evaluated the concentrations of TNF-α, IL-2, INF-γ, IL-10, and selected nitrosative stress parameters (NO, peroxynitrite, S-nitrosothiols, and nitrotyrosine) in NWS and SWS, as well as the plasma of psoriasis patients." (PMID 32164227, 2020). "The expressions of crucial inflammatory mediators (including IL-1β, IL-2, IL-6, IL-10, IL-17, IL-22, IL-23, IFN-γ, TNF-α) in skin tissues were measured by ELISA due to the import role of inflammatory cytokines in psoriasis." (PMID 31181689, 2019). "Therefore, LCs may directly prevent psoriasis aggravation via IL-10 and PD-L1." (PMID 25216727, 2014). "Apremilast is a PDE4 inhibitor that increases levels of cyclic adenosine monophosphate (cAMP), which activates the protein kinase A and modulates the cytokines involved in the immune response of psoriasis (decreases TNFα, IL23, and IFNγ and increases IL10)." (PMID 24069534, 2013). "Gene interaction analyses highlighted IFNG, IL4, IL10, MMP9 and TIMP1 in IBD; IL10, IL13 and PTGS2 in psoriasis; IL8, IL10 and PTGS2 in RA." (PMID 20444268, 2010). "In psoriasis, the cytokine expression profile is selectively skewed toward a T1 (i.e., IL-2, TNF-α, IL-12, IFN-γ) and away from a T2 (i.e., IL-2, IL-5, IL-6, IL-10, IL-13) pattern." (PMID 20040934, 2008). "The proportions of pro-inflammatory (TNF-α, IL-6, IL-17, IL-23, and IL-1β) and anti-inflammatory (IL-10) cytokines were assessed in the serum and cutaneous tissue of psoriatic animals produced by IMQ to assess the immunomodulatory impact of ERN in psoriasis-like inflammation." (PMID 40667480, 2025). "In the early course of the disease, psoriasis patients express high levels of IFN-γ, which shifted toward IL-10 secretion in chronic patients, suggesting a possible shift from Th1 to Th2 response as an adaptation of the immune system to down-regulate inflammatory Th1 response." (PMID 38793117, 2024). "Notably, IL-10-producing Bregs have been reported to be impaired and inversely correlated with IL-17- and IFN-γ-producing T cells in patients with psoriasis." (PMID 38617532, 2024). "Here, we investigated the expression of psoriasis-related cytokines (TNF-α, IL-6, IL-22, IL-23, IL-17A, IL-17E, IL-17F, IL-4 and IL-10) in the inflamed skin after mannan exposure at the peak (day 4) and the end (day 7) of psoriasis with/without inhibitor(s) treatment." (PMID 38444844, 2024). "Another study found that TNFi therapy in psoriasis and IBD patients led to increased peripheral IFN-γ, IL-17, IL-10 and the proliferative response of CD4+ T-cells to T-cell receptor stimulation, while biopsied target tissues showed decreased Th1/Th17 cytokines and inflammatory genes." (PMID 37681925, 2023). "After treatment with IMQ, IL-10−/− mice showed a psoriasis-like phenotype, whereas DKO mice did not." (PMID 37717073, 2023). "Although the cytokines such as IL-4, IL-10, and IL-13 play a relevant role in the pathophysiology of psoriasis, the corresponding inhibitors in clinical trials have not yet achieved the expected efficacy." (PMID 36618400, 2022). "Therefore, we investigated the effects of IL-10 neutralization on T cells and T cell cytokine expression in the IL-23/IL-17-dependent IMQ-induced psoriasis mouse model." (PMID 34616394, 2021).
psoriasis (continued). "We determined the mRNA expression levels of several inflammatory cytokines that are important in psoriasis (TNF-α, IL-23p19, IL-17A, IL-22, IFN-α, IL-1β, IL-6, and IL-10) and a chemokine that promotes the migration of neutrophils (CXCL2) using quantitative real-time PCR." (PMID 32752186, 2020). "Moreover, the concentration of IL-10 (↓29.09%, p = 0.03) in NWS of patients with hyposalivation was significantly lower than in the group of psoriasis patients with normal saliva secretion." (PMID 32164227, 2020). "Most publications have described that IL-10 levels are decreased in the patient serum, but some authors have also reported that IL-10 serum levels were not changed in psoriasis, which is in line with our data." (PMID 32382290, 2020). "In a mouse model of psoriasis (K5.hTGF-b1 transgenic mice), 4-week PUVA treatment suppressed the IL-23/Th17 pathway while augmenting the frequencies of Th2 and IL-10 secreting Foxp3 + Treg, in a CTLA-4 dependent manner, and the levels of many inflammatory cytokines were reduced." (PMID 31533744, 2019). "The levels of pro-inflammatory cytokine IL-2 was increased above normal in mononuclear cells of both forms of psoriasis, while anti-inflammatory IL-10 levels were not changed in psoriatic patients." (PMID 31480263, 2019). "Serum levels of IL-1β, IL-4, IL-10, IL-12, IL-17, IL-21, IL-23, visfatin and omentin were not significantly different between psoriasis patients and controls (all P > 0.05)." (PMID 29416693, 2018). "IL-10 therapy was also tested in phase II clinical trials in IBD and psoriasis." (PMID 29887861, 2018). "This may have been due to a direct induction of IL-10 by apremilast, as had been observed, to elevate IL-10 production by endotoxin-stimulated PBMC, and in the skin of psoriasis patients who achieved a clinical response PASI-75 or greater." (PMID 25973439, 2015). "Apart from significant genetic association of Hepatitis C virus clearance with IL10/19 and IL20, and psoriasis with IL19/20 and IL24, to our knowledge no additional disease association studies with these cytokine genes have been conducted." (PMID 16959027, 2006). "Therefore, these controversial study results cannot unequivocally confirm IL-10 as a reliable biomarker for psoriasis." (PMID 33669402, 2021). "In psoriasis, the absence of Th2-defining cytokines [interleukin (IL)-4, IL-5, and IL-10] and the increased presence of Th1 cytokines (interferon gamma (IFN-γ), tumor necrosis factor (TNF) and IL-12) prompted researchers to classify psoriasis as a Th1-mediated disease." (PMID 31019502, 2019). "Flow cytometry was used to analyze the expression of iNOS and IL-10, which were secreted by MDSCs in mice with IMQ-induced psoriasis treated with or without IL-35." (PMID 36969174, 2023). "In conclusion, we show that T-helper cells, cytotoxic T cells and B cells from a subgroup of patients with psoriasis respond to challenge with citLL37, but not native LL37, with production of IFN-γ accompanied by production of IL-10 by CD4+ T cells." (PMID 38173716, 2023). "Herein, we found that the population of MDSCs secreting iNOS, but not IL-10, was significantly increased in the IMQ-induced mouse psoriasis model." (PMID 36969174, 2023). "Moreover, when IMQ was applied to both ears and shaved back skin in the long-term IMQ-induced chronic psoriasis model, approximately 50% of the IMQ-treated IL-10−/− mice failed to survive." (PMID 37717073, 2023). "In patients with at least a 75% improvement in Psoriasis Area and Severity Index (PASI-75) response, the downregulation of most of these genes was greater than in the nonresponders, yet the expression of IL-10 was increased in responders compared with nonresponders." (PMID 25973439, 2015). "Thus, the lack of IL-10 expression under the TLR7 signaling and the constitutive upregulation of IL-23 in DCs could result in the exacerbation of imiquimod-induced psoriasis-like skin inflammation." (PMID 32456211, 2020).